PML (PML nuclear body scaffold)
Diseases named in the same sentence as PML in open-access papers (continued):
Sharing a sentence is not in itself a finding about the gene and the disease.
cancer (continued). "We suggest that the careful analysis of key upstream molecules that act upon PML in different cancer types will be a strategic approach toward rationally defining targets for the design of specific anti-cancer therapies with a capacity to restore functional PML." (PMID 23730625, 2013). "Thus, a full understanding of PML ubiquitination mechanisms in different cancer types and cellular conditions would aid in the design and selection of specific anti-cancer strategies for treating cancer patients displaying aberrant PML degradation." (PMID 22935031, 2012). "Importantly, recent evidence has emerged that multiple pathways govern PML degradation in tumors and different types of cancers likely use distinct mechanisms to regulate PML stability." (PMID 22935031, 2012). "Since PML NBs are important for apoptosis and negatively affect cancer development, our results suggest that EBNA3B may contribute to cell immortalization and/or malignant transformation by EBV by disrupting PML NBs." (PMID 18617993, 2008). "Moreover, circRNAs have also been implicated in the pathogenesis of acute promyelocytic leukaemia (APL), and the most common chromosomal translocation of PML/RARa in patients with APL leads to the abnormal formation of cancer‐specific circRNAs that promote cancer cell survival." (PMID 40099939, 2025). "In the two decades between the initial discovery of the clinical benefit of atRA in APL and the mechanistic dissection of the PML-RARα fusion oncoprotein, more than 100,000 patients were enrolled in randomized controlled trials testing various retinoid pathway agonists to prevent cancer." (PMID 41210994, 2025). "However, recent research indicates that the PML NB may function as a sensor for ROS in two ways: protecting cancer cells from excessive ROS or promoting ROS-induced apoptosis." (PMID 38110976, 2023). "Notably, PML has been reported to function as a tumor suppressor in many cancer types." (PMID 34625711, 2021). "Furthermore, Pin1 also inhibits Rb- and PML-induced senescence in cancer cells." (PMID 33807199, 2021). "However PML and Rb are downregulated by Pin1 in various human cancers." (PMID 33807199, 2021). "Finally, we showed that inhibition of CHK1 phosphorylation further sensitized cancer cells to mitomycin C. Taken together, these findings suggest that the PML is critical for damage-induced CHK1 phosphorylation, which is important for FA gene expression and for repairing ICLs." (PMID 34360546, 2021). "However, PML and pRb are downregulated by Pin1 in numerous cancers." (PMID 30158600, 2018). "Therefore, targeting PML could be an approach to reduce the population of drug-resistant cancer cells." (PMID 29416846, 2018). "Based on our results in U2OS cells and our analysis of cancer transcriptomes, it is likely that reduced PML expression observed in these cancers is correlated with reduced DDIT4 expression, which in turn could promote mTOR activation and promote cancer cell growth." (PMID 28332630, 2017). "Our data indicates that, under normal conditions, PML NBs play an important role in maintaining basal DDIT4 gene expression and that PML loss can lead to dysregulation of DDIT4 expression and therefore inappropriate mTOR activity that could drive cancer growth and progression." (PMID 28332630, 2017). "However, it remains unclear how to reconcile PML's tumor suppressive effects on cancer growth versus its oncogenic activities in enhancing lipid metabolism in different cellular and pathological contexts." (PMID 27058621, 2016). "Additionally, PML regulates cancer cell metabolism and suppresses cancer stem cell maintenance." (PMID 27042198, 2016).
cancer (continued). "A better understanding of the role of PML in non-dividing cell types such as neurons will allow for a more complete picture of the wide range of PML’s functions and may even help provide insight into the functions that are disrupted when PML expression is misregulated in certain cancers." (PMID 24062991, 2013). "The amplification-free, sequencing-based CENAS approach is designed to rapidly detect PML::RARA fusions in APL patients at initial diagnosis, with a high percentage of APL cancer cells (>20%)." (PMID 39766302, 2024). "HS-dependent deposition of DAXX, a PML client, at peri-centromeric heterochromatin was detected, while DAXX was sequestrated in PML-NBs in normal conditions in cancer cell lines." (PMID 35579421, 2022). "All the significant nine representative terms covered 16 genes with 6 NCG cancer genes CTNNB1, PML, RB1, MLL2, ARNT and NRIP1 belonging to at least three representative terms." (PMID 34504716, 2021). "PML regulates metabolism by modulating PGC-1α activation, a key regulator of mitochondrial functions in physiology and in cancer metabolism." (PMID 30244973, 2019). "Therefore, PML-NBs may play a significant role in apoptosis and cancer." (PMID 31088931, 2019). "This feature is often associated with translocation of TRIM genes and creation of oncogenic fusion products, as in the case of TRIM19/PML, TRIM27/RFP and TRIM24/TIF1α, but they can influence cancer progression also per se." (PMID 30974870, 2019). "Although this mechanism is required for hematopoietic and cancer stem cell renewal, the changes in body mass and high AMPK activation in metabolic tissue in Pml knockout mice suggest a broad spectrum of PML-mediated metabolic regulation." (PMID 29416846, 2018). "We found potentially druggable fusions across 29 cancer types, with major recurrent druggable targets in PRAD (TMPRSS2, 205 samples), THCA (RET, 33 samples), and LAML (PML–RARA, 16 samples)." (PMID 29617662, 2018). "CK2 is an oncogene that regulates PML and ZC3H8-localized nuclear bodies, and is also a potential therapeutic target in the treatment of cancer." (PMID 30041613, 2018). "Although some cancer cells in the As2O3-treated xenografts remained to be SOX2 positive (GSCs), these SOX2 signal almost overlapped with the PML staining, and the majority of SOX+ cells (GSCs) were also PML-positive." (PMID 26510911, 2015). "The intense research that followed the landmark discovery linking PML to APL pathogenesis, revealed that PML acts as a tumor suppressor in many other cancer types and is a master regulator of major cellular processes." (PMID 23730625, 2013). "UHRF1 was demonstrated to target PML for degradation by mediating its polyubiquitination in human umbilical vein endothelial cells (HUVEC) and cancer cell lines." (PMID 23730625, 2013). "Quite a few E3s have been identified to mediate the proteasomal degradation of PML, including KLHL20, UHRF1, UBE3A and RNF4, which may drive the development of cancers at least partially through PML downregulation." (PMID 40002221, 2025). "Again, both 21NT and BT474 showed an increase in PML post treatment with epitalon to levels higher than the untreated controls, suggesting that ALT has been activated and is responsible for the increase in telomere length seen in the cancer cells." (PMID 40908429, 2025). "Herein, we found that histone lactylation enhances ALKBH3 expression and simultaneously attenuates the formation of tumor-suppressive promyelocytic leukemia protein (PML) condensates by removing the m1A methylation of SP100A, promoting the malignant transformation of cancers." (PMID 38118002, 2024). "PML, C3, TXN, KRT6C, F2, PTK2, TNF, which could enable HIF-mediated inflammatory response during cancer development." (PMID 36845724, 2023). "Beyond APL, PML-facilitated KAP1 repressive functions may actually contribute to senescence, viral latency or cancer stem cell biology." (PMID 36175410, 2022).
cancer (continued). "HIF1α and PML-RAR; genes that participate in cancer promotion and metastasis." (PMID 34944416, 2021). "As in cancer research, ND10 nuclear bodies are traditionally considered as antiviral restrictions, in which the main components such as PML, Sp100, and the Daxx/ATRX complex are involved in inhibiting viral DNA transcription/replication via IFN response or chromatin repression." (PMID 33546431, 2021). "Moreover, CSNK2A1 renders cancer cells resistant to apoptotic stresses by activating BCL2 and suppressing PML, FOXO3, and PARP1." (PMID 34359939, 2021). "Because PML-RARα is a critical fusion gene in the NB4 cell line and it is involved in the transcriptional misregulation in cancer pathway (KEGG pathway hsa05202), we next investigated the effect of OGP46 on transcriptional and protein level of PML-RARα in NB4 cells." (PMID 33748146, 2021). "In addition to its regulatory role in PML/PML-RARα oncogenic signaling, PIAS1 has been shown to be involved in the cancer therapeutic mechanism of arsenic trioxide (ATO)." (PMID 32047143, 2020). "Furthermore, oncogenes like Akt/PKB and FATE1, and tumor suppressors like PML and PTEN, can play additional roles in the development of cancer via Ca2+-signaling modulation." (PMID 29491433, 2018). "Surprisingly PML protein colocalized at telomeres in both K14Cre;TRF2f/f;Terc-/- (51%) and K14Cre;TRF2+/+;Terc+/+ (45%) SCC cells which was also observed in Terc null (43%) and TRF2 null (49%) cancers." (PMID 29113290, 2017). "Thus, these analyses suggest that PML likely plays a role in regulating DDIT4 gene expression in multiple cell types and cancers of diverse tissue origin." (PMID 28332630, 2017). "In our comparison of the expression levels of target genes in fusion-positive with fusion-negative samples in each cancer type, we found four TFFGs (PML-RARA, RUNX1-RUNX1T1, TMPRSS2-ERG, and SFPQ-TFE3) that had 50 DETGs." (PMID 29299133, 2017). "In contrast, PML has also been shown to behave as an oncogene or pro-survival factor that activates PPAR signaling and enhances fatty acid oxidation to maintain stem cell self-renewal and promote cancer cell survival." (PMID 27058621, 2016). "Although this inhibitor has been shown to exhibit potent anti-cancer activity by targeting NEDD8, it remains to be demonstrated whether PML is also involved in this mechanism." (PMID 23730625, 2013). "It is indeed possible that PML expression is confined to the CSCs and absent in the more differentiated cancer progenitors." (PMID 23847764, 2013). "Despite this centrality in mediating apoptosis or cell-cycle arrest, PML inactivation is not sufficient to increase the rate of spontaneous cancers in mice." (PMID 23847764, 2013). "Thus, the Roc1-Cullin3-KLHL20 complex represents the first PML ubiquitin ligase that is dysregulated in human cancers and the KLHL20-mediated PML destruction and HIF-1α feedback regulation contribute significantly to tumor progression." (PMID 22935031, 2012). "Given a frequent ERK2 activation in various types of human cancers, the ERK2/PML axis may contribute to PML degradation in certain cancers." (PMID 22935031, 2012). "First, the cell lines analyzed in the present study were telomerase-positive cancer cell lines and not cell lines with alternative lengthening of telomeres (ALT), in which ALT-associated PML bodies occur, and in which some PML body dynamics have been reported." (PMID 19014413, 2008). "Additionally, it has been shown that PML is crucial for the alternative lengthening of telomeres, a specific type of HR dependent on break-induced replication in cancer cells that do not express telomerase." (PMID 39388244, 2024).
cancer (continued). "Thus, PML orchestrates mESC state by coordinating SUMO2-conjugation of different transcriptional regulators, raising new hypotheses about PML roles in cancer." (PMID 36175410, 2022). "For this reason, we focused on four MYC-interacting proteins, i.e., Promyelocytic leukemia protein (PML), Glycogen synthase kinase-3 beta (GSK3B), Cyclin-Dependent Kinase Inhibitor 2A (CDKN2A), and Histone deacetylase 2 (HDAC2), which were reported to be mis-regulated in cancer in previous studies." (PMID 36303724, 2021). "Furthermore, perturbed regulation of PML has been found in a variety of cancers without chromosomal translocations." (PMID 32751183, 2020). "To confirm whether transient ALT/telomeric HR-repair is involved in the processing of X-rays-induced DNA damage at telomeres, we checked some of the hallmarks used to define ALT in cancer cells such as TSCE and colocalization of PML (or RPA2) with telomeric DNA." (PMID 31336873, 2019). "Interestingly, HIRA’s localization to PML bodies was impaired in several, but not all, cancer cell lines." (PMID 28981850, 2017). "Under normal conditions, PML forms a protein complex with IP3R3, AKT, and protein phosphatase 2 (PP2a), which regulates cell fate by increasing mitochondrial calcium and apoptosis, but, in cancer cells, the expression of PML is generally low, making them resistant to cell death." (PMID 28074080, 2016). "Curiously, genomic deletion of PML in human cancer cells failed to abrogate the cytotoxic effects of CGs and other apoptotic stimuli such as ceramide and arsenic trioxide that were previously shown to function through PML in mice." (PMID 27031987, 2016). "In many types of cancers, down-regulation of PML protein, but not its mRNA, is observed." (PMID 26539288, 2015). "Human and zebrafish genomes are 70% similar based on conservation of individual genes, with several cancer-associated genes found in mammals but not in the zebrafish, including BRCA1, p16 (CDKN2A), BRCA1, LIF, OSM, IL6 and PML (G.D. and J.N.B., unpublished observation)." (PMID 24973744, 2014). "Therefore, the decline in the number of PML-NBs seems not to be related with the presence of cancer." (PMID 24694011, 2014). "We were particularly interested in examining PML NBs in the context of NPC because the disruption of PML NBs, or lack of the PML protein, is a factor in the development of several types of cancer and because DNA viruses are known to have mechanisms to disrupt PML NBs." (PMID 18833293, 2008). "The involvement of PML as a positive regulator of telomere maintenance on one hand suggests that its function may prevent genomic instability, on the other, it may grant telomerase-negative cancer cells a way to overcome replicative senescence." (PMID 23847764, 2013). "In addition, genotoxic drugs such as etoposide trigger cellular senescence in normal and cancer cells via persistent activation of Janus kinase/signal transducer and activator of transcription (JAK/STAT) signaling and expression of IFN-stimulated genes including PML." (PMID 23730625, 2013). "However, in contrast, some report suggests that increased expression of PML was observed in several carcinoma cells and might be functionally related to cellular growth, indicating all PML will not be functionally equivalent in various cases." (PMID 19025608, 2008). "In contrast, IFN stimulation of carcinoma cells (U2OS, SAOS, HeLa, and A549) failed to induce the recruitment of HIRA to PML-NBs, even though these cell types expressed similar levels of HIRA mRNA and protein within the nucleus." (PMID 30901352, 2019).
cancer (continued). "In contrast, DEGs with lower expression in patient relative to healthy control fibroblasts were enriched for one KEGG category ('Pathways in Cancer' as represented by the SMAD3, LAMA4, PML and DAPK1 genes), but no GO categories." (PMID 23036268, 2012). "Interestingly, the four TFFGs (PML-RARA, RUNX1-RUNX1T1, TMPRSS2-ERG, and SFPQ-TFE3) with the highest MAII scores showed 50 differentially expressed target genes (DETGs) in fusion-positive versus fusion-negative cancer samples." (PMID 29299133, 2017).